TNF (tumor necrosis factor)
Diseases named in the same sentence as TNF in open-access papers (continued):
Sharing a sentence is not in itself a finding about the gene and the disease.
tumor (continued). "More importantly, NETs induce the generation of proinflammatory cytokines such as IL‐8, IL‐6, and TNF‐α, which further increase neutrophil recruitment and NETs formation, thereby promoting tumor immune escape and accelerating the process of metastatic invasion of tumors." (PMID 40979214, 2025). "Despite their known effects on immunomodulation, the combined impact of IFN-γ and TNF-α on tumor cell recognition and apoptosis by NK cells, as well as the infiltration of NK cells into the TME, particularly in the context of tumor spheroids, remains poorly explored." (PMID 41102150, 2025). "Targeting CAF‐associated pathways, M2 macrophages, and TNF‐⍺ signaling could be novel therapeutic strategies for CMS4 PM‐CRC, as they might alter the tumor immune interplay and improve immunotherapy response." (PMID 39739693, 2025). "Furthermore, TNFα is a central cytokine in cancer-related inflammation and correlates with tumor stage and lymph node involvement in colon and colorectal cancer." (PMID 41444742, 2025). "Cytotoxic CD8+ T cells are the preferred immune cells targeting cancer, which exert specific cytotoxic effects by binding to the antigen peptide-MHC class I complex on the surface of tumor cells through perforin/granzyme pathway, Fas/FasL pathway, and TNF-TNFR pathway." (PMID 40430847, 2025). "Additionally, TNF is responsible for promoting the expression of angiogenic factors and enhancing tumor metastasis." (PMID 40699726, 2025). "However, their capacity to eliminate tumor cells, secrete inflammatory mediators (such as TNF-α and IFN-γ), proliferate, and form long-term memory cells can be impaired through T-cell receptor desensitization." (PMID 40843004, 2025). "High concentrations of TNF-α are able to induce the apoptosis and necrosis of tumor cells by binding to TNFR1/2 on the tumor cell surface, whereas IFN-γ and TNF-α can inhibit the expression of Bcl-XL in tumor cells and thus increase the susceptibility of tumor cells to TRAIL-mediated apoptosis." (PMID 40481182, 2025). "Moreover, TAS-115 significantly attenuated tumor-promoting cytokines, including TNF-α, IL-6, and VEGF-α, suggesting a potential role in modulating the inflammatory TME." (PMID 41289612, 2025). "The presence of micrometastatic tumor cells in the liver may also activate Kupffer cells to produce a variety of cytokines (IL-1b, IL-6, TNF), which regulate albumin synthesis by hepatocytes." (PMID 40004975, 2025). "TNF-α exerts tumor-protective functions by activating pro-survival signaling pathways (e.g., NF-κB), inducing a tumor-associated inflammatory microenvironment, suppressing tumor immune responses, and promoting tumor cell survival, invasion, and drug resistance." (PMID 40695795, 2025). "In vitro research using murine BV2 microglial cells demonstrated that conditioned media from glioma cells might activate microglial cells by increasing the mRNA levels of cyclooxygenase-2 (COX-2), tumor TNF-α, IL-6, iNOS, and IL-1β." (PMID 40727443, 2025). "This implicates that Macro_CCL4-derived TNF might be instrumental in orchestrating the immune response within the tumor microenvironment." (PMID 40520886, 2025). "The C3a/C3aR pathway activates the p38 MAPK pathway, leading to TNF-α production and tumor growth." (PMID 41300283, 2025). "This suggests that the inhibition of IL-6 and TNF-α could lead to reducing tumour growth and improving patient outcomes." (PMID 40544399, 2025). "This cellular infiltration is accompanied by robust expression of Th-1-associated cytokines, including IL-2, TNF-α, IFN-γ, and the inducible nitric oxide synthase (iNOS) enzyme, all of which contribute to effective anti-tumor immune responses and tumor clearance." (PMID 40725420, 2025). "In some instances, p38 MAPK cooperates with TNF-α to induce apoptosis in tumor cells." (PMID 41450917, 2025).
tumor (continued). "This variability may be due to the dual role of TNF-α, which can exhibit either pro-apoptotic or tumour-promoting effects depending on the local immune and molecular environment." (PMID 41465261, 2025). "This pathway is known to upregulate the expression of oncogenes such as c‐Myc and Bcl‐2 while enhancing the production of inflammatory cytokines like interleukin‐6 (IL‐6) and tumor necrosis factor‐alpha (TNF‐α), thereby creating a tumor‐promoting microenvironment." (PMID 40387523, 2025). "Notably, TNFα-secreting macrophages can drive PDAC cells toward a more aggressive identity whereby tumor cells and macrophages display extensive crosstalk." (PMID 40634284, 2025). "By activating cytotoxic T cells and NK cells, TNF-α enhances its anti-tumor effects." (PMID 41376630, 2025). "We previously showed a role for TNF signalling in regulating tumour progression in a Ras-dependent Drosophila cancer model and, indeed, removing just one genomic copy of the TNF pathway mediator dl was sufficient to significantly suppress tumour-induced animal lethality." (PMID 41188521, 2025). "Furthermore, the bacterial epitope recognition enhanced broader tumor immunogenicity, inducing robust production of TNF-α and IFN-γ in CD4+ T cells alongside the expected Th17 response." (PMID 41441899, 2025). "Anti-TNFα therapy may inadvertently promote a tumor-promoting microenvironment by reducing the synthesis of anti-tumorigenic cytokines and increasing the expression of pro-tumorigenic factors." (PMID 40282506, 2025). "The tumor microenvironment releases proinflammatory cytokines, including TNF-α and IL-6." (PMID 41002580, 2025). "Cytokines in tumor microenvironment such as tumor necrosis factor-α, interleukin (IL)-6, IL-10 and transforming growth factor-β may enhance this process, promoting tumor cell proliferation and survival, thereby affecting tumor spread to hematological system." (PMID 41221526, 2025). "Mechanistically, ALI may affect prognosis through two pathways: firstly, high NLR reflects systemic inflammation, which promotes the release of pro-inflammatory cytokines (such as IL-6, TNF-α) and drives tumor invasion via the STAT3 pathway." (PMID 40535131, 2025). "However, sustained TNF-α signaling in the tumor microenvironment has been shown to induce MUC4 expression, which masks the HER2 epitope and reduces trastuzumab efficacy, thereby facilitating immune evasion." (PMID 41400702, 2025). "Conversely, mast cells also play antitumor roles by stimulating immune responses, recruiting cytotoxic T cells and NK cells, secreting cytotoxic mediators such as TNF-α and ROS, and enhancing immune surveillance through dendritic cell maturation and tumor antigen presentation." (PMID 40313959, 2025). "Additionally, γδ T cells produce pro-inflammatory cytokines such as IFN-γ and TNF-α, which enhance their anti-tumor activity by promoting the activation of other immune cells, including CD8+ T cells and NK cells, involved in the anti-tumor immune response." (PMID 40867289, 2025). "Such evidence across malignancies supports the concept that TNF-α reflects tumor aggressiveness and could be broadly prognostic." (PMID 40299527, 2025). "In particular, concurrently administering anti-PD-L1 targeted therapies alongside TNF-α could yield better therapeutic outcomes in suppressing tumor progression." (PMID 40909948, 2025). "In the tumor microenvironment, all types of cytokines are involved in intercellular communications including interleukins (ILs), interferons (IFNs), the tumor necrosis factor (TNF) superfamily, chemokines, and growth factors." (PMID 40181971, 2025). "RNF31 inhibition sensitizes tumours to NK and T cell‐mediated killing through TNF‐driven pathways." (PMID 40673641, 2025). "TNFα is a pro-inflammatory cytokine triggering and intensifying the body’s inflammatory response to combat infections or other harmful stimuli, but it can also promote tumor growth and progression under certain conditions." (PMID 40743051, 2025).
tumor (continued). "Notably, IFN-γ and TNF-α can synergize to trigger caspase-8–dependent tumor cell death, which is compatible with the increased cytotoxicity observed in our assays." (PMID 41455906, 2025). "Differentiation of tumor cells with IFN-γ and TNF-α was found to slow tumor growth substantially." (PMID 40805135, 2025). "Given the observed effects of TNF EVs promoting migration and inducing a tumor stem cell-like phenotype in MCF-7 cells, we sought to explore whether these vesicles also contribute to endocrine resistance." (PMID 40567500, 2025). "Research shows that these engineered macrophages produce a range of pro-inflammatory cytokines, such as interferon-gamma (IFN-γ), tumor necrosis factor-alpha (TNF-α), and interleukin-12 (IL-12), which are essential for generating a strong anti-tumor immune response." (PMID 40308592, 2025). "Once activated, CAR-M secretes TNF-α, a cytokine that triggers apoptosis in tumor cells." (PMID 41181137, 2025). "Furthermore, this study demonstrated that oral administration of the CB‐AKK combined bacteria significantly increased the levels of TNF‐α in both tumor tissues and serum, whereas simultaneously reducing the levels of IL‐6 and IL‐10." (PMID 40497373, 2025). "Low-dose radiation may reshape the TME by polarizing macrophages to a M1 phenotype, increasing TNF-alpha and IL-12, and promoting normalization of tumor vasculature to improve oxygenation and immune infiltration." (PMID 41487560, 2025). "Cytokine analysis of tumor tissues revealed that the combination of Liensinine and immunotherapy significantly elevated levels of pro-inflammatory cytokines, including TNF-α, IL-12, IFN-γ, and granzyme B, while reducing the levels of immunosuppressive cytokines, such as IL-10 and TGF-β." (PMID 40665352, 2025). "Therefore, the MMW-induced alteration in the cytokine secretion profile (increased IL-12/TNF-α and decreased IL-10) likely contributes to the enhancement of macrophage anti-tumor function." (PMID 41383334, 2025). "Additionally, they produce cytokines such as IFN-γ and TNF-α, which enhance immune responses by upregulating antigen presentation and inhibiting tumor angiogenesis through VEGF downregulation." (PMID 40539049, 2025). "Furthermore, TNF-α represents only one component within a broader pro-tumor inflammatory network; monotherapeutic targeting using agents such as infliximab has demonstrated limited efficacy and potential risks in solid tumors." (PMID 41000397, 2025). "Under specific tumor microenvironments (e.g., chronic inflammation, persistently elevated TNF-α levels), HMGCR and TNF-α may form intricate regulatory networks that either antagonize or synergistically promote inflammatory cell death." (PMID 41450917, 2025). "To account for additional effector functions of CAR-NK cells besides direct tumor cell killing, we tested TNFα and IFNγ secretion of CD276-directed CAR NK-92 cells after co-incubation with all target cell lines tested before in cell killing experiments (except AR6)." (PMID 40469103, 2025). "High TNF-α has also been linked to poor chemotherapy response in some observations: patients with elevated TNF-α were more likely to have chemoresistant disease, possibly due to TNF-induced survival pathways and anti-apoptotic proteins in tumor cells." (PMID 41007766, 2025). "In the tumor microenvironment, macrophages are the primary source of TNFα." (PMID 40895569, 2025). "Likewise, adoptively transferred anti-tumor CD8+ T cells harboring a deletion of TNFAIP3 enhanced IFN-γ and TNF-α production and reduced PD-1 expression, which exhibited superior anti-tumor activity in vivo." (PMID 40469292, 2025). "Moreover, ELISA quantification confirmed a significant decrease in the pro‐inflammatory cytokines TNF‐α and IL‐1β in tumor tissues following FPHPE administration." (PMID 41200213, 2025).
tumor (continued). "Additionally, elevated LDL levels correlate with increased levels of proinflammatory cytokines, such as IL-6 and TNF-α, which are thought to support tumor growth and metastasis." (PMID 41245411, 2025). "Thus, monocytes and macrophages, which can make up to 50% of the tumor mass and are mostly activated as M2-like macrophages, can secrete many of the cytokines associated with EMT, including TGFβ, TNFα and IGF1." (PMID 41462963, 2025). "While immune cells are widely recognized as the primary source of TNF-α, autocrine production by cancer cells also plays a significant role, particularly under conditions where NF-κB is constitutively activated within the tumor microenvironment." (PMID 40149421, 2025). "TNF-α exhibits anticancer properties by inducing necrosis in tumor tissues." (PMID 40670983, 2025). "However, cytokines secreted by tumor cells, such as G-CSF, IL-1β, IL-6, and TNF, can extend their longevity." (PMID 41280929, 2025). "In addition, the expression level of METTL1 was positively correlated with that of WDR4 and TNF-α in PTC tumor tissues, and WDR4 expression was also positively correlated with TNF-α expression." (PMID 40360483, 2025). "In addition, the expression of TNF-α was significantly higher in CD103+ DCs from tumor-bearing Tgfbr2MyeKO mice." (PMID 40568095, 2025). "In our investigation, TNF-α expression was more frequently associated with non-malignant tumor features." (PMID 40869161, 2025). "It is now widely accepted that most T-lymphocytes undergo “exhaustion” in response to continuous stimulation by tumor cells, which is characterized by a decrease in effector-related molecules (IFN-γ, TNF, and granzymes), as well as a loss of stemness and proliferation potential." (PMID 40115790, 2025). "Due to immunosuppression, there is concern that systemic steroids, cyclosporine, and tumor necrosis factor alpha inhibitors may interfere with ICI anti-tumor activity or exacerbate active malignancy." (PMID 39845461, 2025). "TNF-α is often described as a double-edged sword in oncology: while initially identified for its tumoricidal effects at very high concentrations, at lower levels such as those produced chronically in the tumor microenvironment, TNF-α tends to promote tumorigenesis." (PMID 40299527, 2025). "However, emerging evidence suggests that TNF-α can exert dual effects in cancer, either promoting carcinogenesis or inhibiting tumor growth depending on the specific cellular context." (PMID 41325308, 2025). "As commented on earlier, tumours actively secrete a variety of cytokines and pro-inflammatory mediators, including IL-6, TNF-α, and IL-1β, which can reach the adipose tissue and trigger the recruitment of immune cells, such as macrophages and T cells, leading to a chronic inflammatory state." (PMID 41373779, 2025). "However, TNF-α exhibits context-dependent effects: under certain conditions, it can also induce apoptosis in tumor cells." (PMID 40558596, 2025). "Within our investigation, most of the subjects who experienced TNF-α fluctuations were patients with disease progression, consistent with prior reports that dynamic TNF-α signaling may reflect both anti-tumor immunity and resistance mechanisms." (PMID 41020868, 2025). "Additionally, S. costus downregulates TNF-α and NF-κB, key mediators of tumor metastasis and chronic inflammation." (PMID 41210686, 2025). "For instance, a high TNF-α level at diagnosis may flag patients with a more advanced inflammatory tumor milieu who might benefit from intensive monitoring or therapy, whereas low TNF-α could suggest a more indolent course." (PMID 40299527, 2025). "Furthermore, mouse basophils can secrete TNF-α and histamine to exert anti-tumor effects, and the granzyme B released by basophils has a cytotoxic effect on cancer cells." (PMID 40131539, 2025). "Moreover, PBMC exposure to untreated tumor supernatants increased TNF-α secretion, consistent with observations in RCC patients." (PMID 41007670, 2025).
tumor (continued). "Given its association with tumor progression, TNF-α represents a novel target for anti-cancer therapy; strategies to inhibit TNF-α (or its downstream effects) might suppress the pro-tumor inflammation that fuels disease spread." (PMID 40299527, 2025). "They found that sMICA hindered the activation of NKG2D signaling in NK cells, reduced the generation of cytokines such as IFN-γ, TNF-α, and IL-8 by NK cells, and decreased the expression of CD107a, a specific marker of NK cell activation, thereby impairing the anti-tumor immune response of the body." (PMID 40563539, 2025). "Moreover, it has been demonstrated that TNF-α, a powerful pro-cancer cytokine, induces shedding of cell surface molecules from tumor cells." (PMID 39955339, 2025). "Lloyd J. Old discovered TNF-α in the 1970s while studying these tumor regression-related factors." (PMID 40430212, 2025). "It remains unclear whether autocrine or paracrine TNF loops are involved in Treg expansion during normal physiology or in conditions like tumor progression." (PMID 40977146, 2025). "In HCC, tumor exosomes carrying fatty acids—particularly palmitic acid—stimulate hepatic macrophages to secrete tumor necrosis factor (TNF), leading to a pro-inflammatory microenvironment that impairs fatty acid metabolism and oxidative phosphorylation, thereby promoting fatty liver progression." (PMID 40881702, 2025). "TNF‐α influences tumor cell invasion by inducing apoptosis and inflammatory responses." (PMID 40040540, 2025). "A common immunopathogenic mechanism across many of these cancers is the activation of the MyD88/NF‐κB axis, which drives the secretion of pro‐inflammatory cytokines (e.g., IL‐6, TNF‐α), promotes angiogenesis, and upregulates anti‐apoptotic genes, thereby creating a tumor‐supportive microenvironment." (PMID 40922674, 2025). "Therapeutic approaches targeting TNF-α signaling encounter anticipated challenges, including the dual role of this pathway in both promoting and inhibiting tumor growth, its dependence on specific contexts, and the established risk of metastasis resulting from uncontrolled inflammation." (PMID 41584509, 2025). "In conclusion, our findings indicate that bystander killing in the context of CD3xHER2 bsAbs involves initial bsAb‐mediated T‐cell cytotoxicity against HER2+ tumor areas and subsequent paracrine killing of HER2− tumor areas through IFNγ and TNFα production by the activated T‐cells." (PMID 40178291, 2025). "Additionally, CD8+ T-cells produce cytokines such as IFN-γ and TNF-α, which enhance antitumor activity by inhibiting tumor cell proliferation and increasing the expression of MHC-I on tumor cells." (PMID 40305493, 2025). "Upon antigen recognition, CTLs execute their cytotoxic functions by secreting granzyme B and perforin, increasing the synthesis and release of cytokines such as interferon-gamma (IFN-γ) and tumor necrosis factor-alpha (TNF-α) and inducing tumor cell apoptosis via the FasL/Fas pathway." (PMID 40458394, 2025). "In contrast, TNF-α directly induces apoptosis in tumor cells." (PMID 40182050, 2025). "While SASP factors such as IL‐6 and TNF‐α may promote immune cell‐mediated clearance of senescent cells, they could also support tumor progression by fostering a pro‐inflammatory microenvironment." (PMID 40186402, 2025). "Synergistic tumor therapy could result from LPFe3O4 NPs’ ability to efficiently rewire M2 to M1 macrophages, activating T cells, releasing TNF-α, and generating large levels of NO, according to both in vitro and in vivo investigations." (PMID 40230883, 2025). "Therefore, while cytokines such as IFN-γ and TNF-α offer promise, their use in the clinical settings requires careful optimization considering the tumor subtype and the balance between NK cell-activation and exhaustion." (PMID 41102150, 2025). "Moreover, upon activation, CAR-NK cells secrete cytokines such as IFN-γ and TNF-α, inhibiting tumor growth and reshaping the immunosuppressive tumor microenvironment." (PMID 40904456, 2025).